ARG1 (arginase 1)
Diseases named in the same sentence as ARG1 in open-access papers (continued):
Sharing a sentence is not in itself a finding about the gene and the disease.
infection (continued). "Indeed, ARG1 was dampened early during Mtb CDC1551 infection of the rabbit lungs that ultimately develops latency, while ARG1 expression was upregulated in the lungs of rabbits with active TB, which is associated with failed immune response." (PMID 27148269, 2016). "After aerosol infection with Mtb, arg1 mRNA was hardly detectable in wild-type mice." (PMID 24979482, 2014). "Arginase 1 and Relmα, both of which are considered to be canonical markers of M2 activation, have been shown to play roles in these processes, although their importance appears to be greater at times later in infection than those tested here." (PMID 25144366, 2014). "Arg1 has also a role in the inflammatory response of macrophages to infection." (PMID 23922979, 2013). "It has been demonstrated previously that during L. major infections high local Arginase-1 levels at the site of infection mediate L-arginine depletion, which results in impaired local CD4+ (and CD8+) T cell function, particularly IFN-γ production but also to a lesser extent IL-4 and IL-10." (PMID 23437409, 2013). "Arg1 levels were still much higher in BMMΦ from obese mice after 24 h infection." (PMID 23922979, 2013). "The existence of multiple pathways for the induction of Arg1 may serve to achieve redundancy in an essential anti-inflammatory effector mechanism functional in many settings of infection, inflammation and wound healing." (PMID 24244174, 2013). "This can be explained by the fact that, although these genes are related to M2, IL-10 can be activated by the NF-κB signaling pathway in the late phases of infection to quell the immune response and arginase-1 is induced following toll like receptor stimulation." (PMID 22817641, 2012). "In each case host factor expression in skin infected by the complemented ΔaaaA mutant matched that infected by the ΔaaaA mutant rather than the WT which is in line with the cfus with the exception of Arg1, which exhibited elevated expression in the complemented ΔaaaA mutant 2 days post infection." (PMID 22927813, 2012). "The error in the measurement of Arg1 at 8 days post infection is higher than for the other genes analysed, thus data must be viewed with caution although loose trends can be identified to inform further studies and maximise the benefit of using an animal model." (PMID 22927813, 2012). "Therefore, to investigate the role of arginase in parasite replication without the potential confounding influence of parasite arginase activity, we used the BHK infection model to knockdown host arg1." (PMID 22275864, 2012). "Treatment of macrophages with IFN-γ and infection by the strains B2 and H37Rv synergistically induced M1 polarization, leading to high levels of inducible nitric oxide synthase (iNOS) expression, and reduced expression of the Arg-1." (PMID 22863292, 2012). "Within 4 days of infection, we detected strong Arg-1 up regulation during RH infection." (PMID 21931552, 2011). "The decline of Arg1 mRNA levels after 96 hours of infection was in toe with fungal clearance." (PMID 21246055, 2011). "We tested the hypothesis that ROP16-mediated arginase-1 expression in infected cells limited the replication and dissemination of the parasite during in vivo infection." (PMID 21931552, 2011). "In addition to aiding host survival, Arg1 has been shown to down-regulate the inflammatory responses observed in response to infection." (PMID 21585399, 2011). "Indeed, there was large increase in infection rate when wild-type parasites entered the host in Arg1−/− MØ compared to Arg1+/+ cells." (PMID 21931552, 2011). "We hypothesized that by abrogating Arg1 function in macrophages, we would see exacerbated infection-induced pathology in T. muris infection." (PMID 21585399, 2011). "Thus, in infections by Nippostrongylus brasiliensis or Schistosoma mansoni, Arg1- and Fizz1-expressing AAMs were shown to be suppressors of Th2 inflammation in the lung." (PMID 21246055, 2011).
infection (continued). "Likewise, the authors reported STAT6-independent arginase-1 induction during infection with Type II ROP16-expressing parasites, a result that also stands in contrast to our findings." (PMID 21931552, 2011). "Infectious burdens, assessed by adult worm pairs and tissue egg counts in the liver and gut, were similar in both Arg1flox/flox and Arg1−/flox;LysMcre mice at all time points, demonstrating that Arg1-deficiency does not affect susceptibility to infection." (PMID 19360123, 2009). "Macrophages recruited to the peritoneum by F. hepatica show all the hallmarks of alternative activation; by 5 days after infection, the expression of markers of alternative activation, Fizz1, Arginase 1 and Ym1 are up-regulated and remain so for the subsequent 3 weeks." (PMID 19478853, 2009). "Although susceptibility to infection was not affected by the conditional deletion of Arg1 in macrophages, Arg1−/flox;LysMcre mice died at an accelerated rate." (PMID 19360123, 2009). "Because Arg1 mRNA and Arg1 protein is predominantly produced by macrophages following infection with S. mansoni, we examined whether Arg1 regulates the pathogenesis of Th2 cytokine driven disease by studying mice with macrophage-specific deletions of Arg1." (PMID 19360123, 2009). "Arginase 1 (ARG1), a typical marker of alternatively activated macrophages (M2), central downstream effector cell of the Th2 response, implied the pronounced activation of M2 and their rapid recruitment both at the onset and at the end of infection." (PMID 18945374, 2008). "Related studies indicated that elevated arginase-1 levels resulted in L-arginine depletion in various immune-related clinical conditions, such as inflammation-triggered immune dysfunction, cancer cell immune evasion, fibrosis, and immune responses to pathogen infections." (PMID 41258798, 2025). "ARG1 is a cytoplasmic enzyme that is expressed in macrophages, bone marrow-derived suppressor cells, dendritic cells, and innate lymphoid group 2 cells in response to Th2-type cytokines (IL-4 and IL-13) and infection with pathogens related to other signaling factors." (PMID 36918848, 2023). "In addition, the inflammatory cytokines Interferon-γ (IFN-γ), tumour necrosis factor α (TNF-α), transforming growth factor-β (TGF-β), and Arginase 1 (Arg-1) were significantly upregulated after the TgCtwh3 infection, while glial fibrillary acidic protein (GFAP) was down regulated." (PMID 37651502, 2023). "Importantly, compared to WT-infected brains, the K101R infection resulted in significantly higher expression levels of genes involved in the regulation of cytokine production and inflammatory response, including Chil3, Arg1, and Mmp8." (PMID 37884553, 2023). "Arg1, which is involved in activating anti-inflammatory responses, was also higher in biofilm-infected tissues than in planktonic bacteria-infected tissues, suggesting a lower ability of P. aeruginosa biofilms to activate proinflammatory responses to infection." (PMID 32903626, 2020). "As the infection progresses, the macrophages exhibit an alternatively activated phenotype with the ability to block lymphocyte proliferative response and express high levels of chitinase-like 3 (Chil3) type 1 (Ym1) and arginase 1 (Arg1), likewise programmed death-ligands 1 and 2 (PD-L1 and PD-L2)." (PMID 30538171, 2019). "Thus, the function of ARG1 appears to depend on the stage of infection." (PMID 30914513, 2019). "Next, we found increased mRNA expression and activity levels of Arg1, mRNA expression of Fizz, Chi3l3, Cd209d, Cd209e, Mrc2 (Cd206), Marco, Il13, Saa1 (Serum amyloid A1 protein), Ccl17, Ccl19, Ccl20, Ccl22, and Ccl24 in Stat2−/− mice compared to WT mice during super-infection." (PMID 30337919, 2018). "Therefore, during in vivo infection, Arg1 expression may be directly inhibited by type I IFN signaling and indirectly inhibited by type I IFN–dependent regulation of TNF and Th2-associated cytokine expression." (PMID 27849167, 2016).
infection (continued). "We showed previously that a gene associated with suppressive myeloid cells, arginase 1 (Arg1), was induced in musculoskeletal tissues and macrophages of mice infected with RRV or CHIKV, and mice that lacked Arg1 expression in myeloid cells had reduced viral loads at late times post-infection." (PMID 26436766, 2015). "Moreover, it is likely that at an early time of infection, with the activation of M2, the induction of Arg-1 could be exploited by TgCtwh3 to promote its growth." (PMID 24499603, 2013). "Furthermore, hamster arg1, which is expressed by macrophages in the infected spleen, is dominant over the level of parasite arginase even though parasite arginase expression increases throughout the course of infection." (PMID 22275864, 2012). "However, interestingly, the Arg1 induction evident 2 days post infection had resided by 8 days." (PMID 22927813, 2012). "Arginase-1 may directly harm parasites, as H. polygyrus exhibited higher levels of cytochrome oxidase, a marker of a stress response, in a secondary infection compared to a primary infection, and this increase was lost following BEC administration." (PMID 23053394, 2012). "We next examined whether ROP16 was involved in arginase-1 induction during in vivo infection." (PMID 21931552, 2011). "Specifically, the addition of FUC caused a further reduction in mRNA expression levels of NHE2, TRPV6, APOA1, APOA4, APOB, APOC3, and ASS1 compared to PEDV infection alone, while FUC supplementation counteracts PEDV-induced ARG1 upregulation." (PMID 40218394, 2025). "Levamisole and 25–100 mg/kg baicalin upregulated the mRNA expression of iNOS and CD86 and attenuated the levels of ARG1, IL-10, and CD163 in the spleen, in contrast with the infection group (p < 0.05)." (PMID 40427533, 2025). "Here, we report that, in the chronic model of infection and therapy, PRK-treated mice showed an increase in the Ym1+Ym2 and arginase-1 (Arg-1) positive population of macrophage in comparison to the H37Rv infected group." (PMID 38756781, 2024). "Firstly, we detected the expression of ARG1 and NOS2, the well-known macrophage phenotype M2 and M1 markers, in lung homogenate on day 3 post-infection by western blotting." (PMID 37704783, 2023). "The results showed that iNOS was restrained, whereas Arg-1 was promoted in the CFT073wt group compared with those in the CFT073∆tcpc group, demonstrating that CFT073wt infection inhibits in vivo M1 but promotes M2 polarization in kidneys of mice with PN." (PMID 36078080, 2022). "The RNA-seq further revealed that the basal expression level of ARG1 was significantly higher in SC283, with further increased after Cs inoculation, while CARG expression was significantly lower both before and after infection." (PMID 35018449, 2022). "After 11 weeks of infection, this profile was altered, with C57BL/6 presenting more M1 markers, while BALB/c showed significantly higher levels of Arg-1 marking in relation to C57BL/6." (PMID 34660334, 2021). "cCasp8 and to a lesser extent cCasp9 were activated by both PRRSV-1 strains after one week post-infection together with a replenishment of both CD163+ and Arg-1+ pulmonary macrophages." (PMID 33482914, 2021). "In addition to an enhanced CD8+ T cell activation in the periphery during the early infection phase, an altered immune environment at the site of infection, including reduced infiltrations of Foxp3+ Treg and arginase 1+ M2-type cells in DCIR−/− animals at 14 dpi might have influenced TMEV control." (PMID 34893671, 2021). "Infection with O. dentatum significantly increased expression of IL4, IL13, ARG1, CCL17 and CCL26, with a concurrent trend for down-regulation of the expression of Th1-related genes such as IL8." (PMID 35069576, 2021). "At the time point coinciding with the second peak of infiltration, 240 h, C57BL/6 mice presented higher marking for both Arg-1 and CD206 at the infection site." (PMID 34660334, 2021).
infection (continued). "The infection of RAW264.7 cells with RSV led to an increased expression of iNOS and IL-1β, as well as the decreased expression of Arg-1." (PMID 34384038, 2021). "RAW 264.7 cells were cocultured with H. pylori at various multiplicities of infection (MOIs), and iNOS, CD86, Arg-1, CD206, and HIF-1α expression was detected by Western blot, PCR, and ELISA analyses." (PMID 33376580, 2020). "We show that F4/80+, CD11b+, CD11cint, CX3CR1+, MHC class II+, Ly6C−, ARG1+, and NOS2+ macrophages accumulate in the small intestine during infections in mice." (PMID 31455692, 2019). "Our laboratory has previously shown that ARG1+, NOS2+ macrophages accumulate in the duodenal lamina propria following infection and resemble myeloid-derived suppressor cells." (PMID 31455692, 2019). "We have previously reported that ARG1, NOS2 dual expressing macrophages accumulate in the intestine following infection with Giardia and used these markers to assess accumulation in this experiment." (PMID 31455692, 2019). "gMDSCs expressed arginase 1, high levels of the inhibitory ligand PD-L1 and the ATP dephosphorylating enzyme CD39 on the cell surface upon infection." (PMID 28835242, 2017). "Infection with La-arg- reduces the levels of CAT2B, CAT1 and ARG1 and allows the expression of NOS2 and NO production in BALB/c macrophages, thereby reducing the infectivity." (PMID 29379478, 2017). "We therefore analyzed the induction of iNOS and arginase-1 protein expression in IFN-γ- and LPS-activated human monocyte-derived macrophages, cocultured with C. albicans (multiplicity of infection [MOI] = 1) for 3 h by immunoblotting." (PMID 28119468, 2017). "Low levels of Arg1 expression were detected in the lungs of WT and Ifnar−/− mice at day 20 post–BTB 02-171 infection." (PMID 27849167, 2016). "We previously demonstrated that specific ablation of Arg1 in myeloid cells enhanced the clearance of RRV from musculoskeletal tissues and diminished muscle tissue pathology at late times post-RRV infection." (PMID 26436766, 2015). "In the in vitro infection model, IGF-1R inhibition reduced parasite-induced expression of host arg1 mRNA and the intracellular parasite load, without decreasing cell viability." (PMID 24967908, 2014). "Most genes were constant or down-regulated (e.g. arginase 1 and 2) upon interaction with Giardia, whereas inducible NO synthase (iNOS) and ornithine decarboxylase (ODC) were up-regulated within 6 h of infection." (PMID 24228819, 2013). "Accordingly, infection of BMDMs with virulent but not less virulent T. cruzi parasites subverts parasite killing by inducing Arg1 expression and downmodulating iNOS expression." (PMID 40852707, 2025). "In line with this, and somewhat unexpectedly, we also did not observe any significant infection-dependent differences in Arginase-1 expression upon infection." (PMID 40794782, 2025). "The mRNA abundance of TNF-α, IL-1β and IL-6 were significantly up-regulated from 6 h to 24 h post infection, while those of iNOS, Arg-1 and IL-10 did not change significantly from 18 h to 24 h post infection." (PMID 40663568, 2025). "Even though infection with CI2 isolate did not increase Arg-1 expression and activity in AAMΦ, the parasite load was higher than the one in the unstimulated BMMΦ but at a lesser magnitude than that observed during infection with the QRO isolate." (PMID 39452749, 2024). "Thus, we analyzed if infection with two T. cruzi isolates with different degrees of virulence resulted in a differential expression and activity of NOS2 and Arg-1 in BMMΦ of CD1 mice." (PMID 39452749, 2024). "In contrast to our expectations, we did not observe a correlation between a reduction in Arg1 and an increase in Nos2, reflecting in changes in NO production upon putrescine supplementation during infection." (PMID 37000792, 2023).
infection (continued). "Further investigation revealed that Arg1 expression was a critical immune regulatory function of CD4+ T cells, suppressing antiviral immunity and facilitating viral chronicity in the context of infection with MCMV." (PMID 37440306, 2023). "In addition, the transcriptional levels of the M1 marker, iNOS, and the M2 marker, Arginase-1, in the macrophages collected from the infected livers, as measured by RT-qPCR, showed the same trends as the CD86+ and CD206+ expression during the infection course." (PMID 36668953, 2023). "As anticipated, single‐cell analysis by flow cytometry revealed that infection with the cps mutant did not increase the levels of Arg1 and CD206." (PMID 36337046, 2022). "Spleens and livers of these mice showed increased expression of arginase-1 and mannose receptor (CD206) and decreased expression of iNOS, IL-12, and IL-23 in bone marrow-derived macrophages after infection with C. burnettii compared to C. burnetii-infected wild-type mice." (PMID 35137689, 2022). "Additionally, by comparing enzymatic activity between macrophages infected or uninfected with C. neoformans we found that infection lowers NOS activity in M0 and M2 populations while increasing Arg1 activity in M1 populations." (PMID 35816543, 2022). "After continuous infection for 12 h, cell-derived exosomes induced M1 polarization of macrophage by enhancing CD11b protein, TNF-α, and iNOS mRNA levels, along with the decrease of Arg-1 mRNA level." (PMID 34136558, 2021). "To identify the profile of macrophages at the infection site, we performed the immunohistochemistry assay to identify the presence of MHC-II and iNOS labeling related to the M1 profile, as well as CD206 and Arg-1 markers, related to the M2 phenotype." (PMID 34660334, 2021). "However, we did note a trend (p < 0.1) for interactions between infection and LB supplementation for the expression, of ARG1, TLR3, IL1B, and CTLA4, with the infection-induced expression of these genes being attenuated to some extent by LB." (PMID 35069576, 2021). "In contrast to the role of ARG1 for the control of infections with other intramacrophage pathogens, deletion or inhibition of ARG1 did not influence the control of systemic S.tm infection in mice." (PMID 34359992, 2021). "When studying Arg1 mRNA expression in the liver, we neither observed an upregulation following infection nor differences between the various genotypes, which is likely due to the high constitutive expression of Arg1 in hepatocytes." (PMID 34359992, 2021). "After 24 h of infection and IL-4 stimulation, we detected the highest levels of ARG1 and iNOS proteins (details not shown)." (PMID 34359992, 2021). "As mice with a universal deletion of ARG1 are not viable, we performed additional infection experiments in which we applied the pharmacological ARG1 inhibitor CB-1158." (PMID 34359992, 2021). "On the contrary, in infections with the Trichuris muris or Leishmania major, mice lacking ARG-1 or ARG-2 showed unaltered cytokine responses, parasite burden and NO production." (PMID 32029006, 2020). "Arg1 was induced, whereas Asl was repressed upon infection, both independent of hepatocyte-intrinsic IFNAR1 signaling." (PMID 31784108, 2019). "The ARG1 enzyme, which catalyzes the hydrolysis of arginine to ornithine and urea, is produced in the liver under the stimulation of IL-4, IL-10, and TGF-β, as well as by immune response cells, such as activated neutrophils at infection sites." (PMID 31320834, 2019). "We further found that STAT3-deficient macrophages expressed less Arginase-1, and that mice lacking STAT3 in the myeloid compartment (LysMCrexSTAT3fl/fl) were unable to reject a secondary infection with H. polygyrus." (PMID 31708913, 2019).